RAD51C (RAD51 paralog C)
Diseases named in the same sentence as RAD51C in open-access papers (continued):
Sharing a sentence is not in itself a finding about the gene and the disease.
cancer (continued). "In summary these results show a proof of principle that Rad51C promoter can be successfully used to target cancer cells." (PMID 24742710, 2014). "This revealed an increase in RAD51B, RAD51C and RAD51D paralogue mutations in human cancers." (PMID 42133623, 2026). "Other homologous recombination DNA damage repair (HR-DDR) genes associated with other cancer risks besides breast and ovarian, such as ATM (n = 9), BARD1 (n = 4), BRIP1 (n = 2), CHEK2 (n = 5), PALB2 (n = 5), RAD51C (n = 1), and RAD51D (n = 7), accounted for an additional 4% (33/769)." (PMID 40065011, 2025). "The spectrum of cancers in the BRIP1-positive families was wider than that of RAD51C&D." (PMID 40282418, 2025). "Therefore, we aimed to investigate the frequency of HRD among patients with cancer with germline PVs in RAD51C/D." (PMID 38648056, 2024). "Indeed, other core HRR-associated genes (BARD1, PALB2, FANCC, RAD51C and RAD51D) are frequently lost in many cancers." (PMID 37298484, 2023). "Concerning the RAD51C gene, the c.1026+5_1026+7delGTA variant was identified in one patient diagnosed with BC at age 49, without a family history of cancer." (PMID 37628581, 2023). "In addition to BRCA1 and BRCA2, many other HRR mediators (ATM, BRIP1, CHEK2, NBS1 or RAD51C) are frequently defective in cancer." (PMID 37298484, 2023). "Although the role of RAD51C and RAD51D have yet to be fully explored in the FC population, it is clear from previous work that investigating the FC population can assist in characterizing new cancer risk genes." (PMID 35565380, 2022). "Our targeted genotyping assays or review of available WES data revealed that none of the carriers identified in the cancer study groups also carried another one of our RAD51C or RAD51D candidate variants." (PMID 35565380, 2022). "A similar enrichment for signature 3 was found for PALB2 and RAD51C mutations or epigenetic silencing of the BRCA1 or RAD51C promoter, but not for inactivation of other cancer-associated genes, such as CHEK2 and ATM." (PMID 33670893, 2021). "Germline variants in the HR pathway, comprising at least 10 genes, such as BRCA1, BRCA2, ATM, BARD1, BRIP1, CHEK2, NBS1(NBN), PALB2, RAD51C, and RAD51D, lead to inherited susceptibility to specific types of cancers, including those of the breast, ovaries, prostate, and pancreas." (PMID 35008774, 2021). "Among these, RAD51C was found constitutively hypermethylated in sporadic BC, as showed by Hansmann and colleagues, who identified hypermethylation at both BRCA1 and RAD51C promoters in 1.4% and 0.5% of high-risk cancer patients, respectively." (PMID 32276467, 2020). "Of notice, in GC, we found the cancer-associated genes LPCAT1 and RAD51C over-expressed in females." (PMID 32849808, 2020). "Several relatives (PID: III‐15; III‐24; III‐28) with other types of cancers (endometrioid, thyroid, kidney) screened negative for the RAD51C c.571 + 4A > G variant." (PMID 31782267, 2020). "Interestingly, we find that deep somatic deletions do frequently contribute to biallelic loss of BRCA2 or RAD51C, occurring in 10% of CHORD-HRD patients pan-cancer." (PMID 33149131, 2020). "This is the largest family-based study to date to estimate age-specific relative and absolute TOC and BC risks for RAD51C and RAD51D pathogenic variant carriers, confirming that RAD51C and RAD51D pathogenic variants are associated with TOC and BC risks, which vary by cancer-family history." (PMID 32107557, 2020). "We identify inactivation of BRCA1, BRCA2, RAD51C, and PALB2 as the most frequent genetic cause of HRD pan-cancer in both primary and metastatic cancer, with the latter two genes resulting in the same mutational footprints as BRCA2 (consistent with the findings of recent studies in breast cancer)." (PMID 33149131, 2020). "Additionally, seven RAD51C heterozygotes (two males; five females) are cancer‐free (age range: 48–78)." (PMID 31782267, 2020).
cancer (continued). "Interestingly, cancers that showed epigenetic silencing of BRCA1 (n = 32, 995) or RAD51C (n = 23, 995), or that carried germline PALB2 (n = 3, 995) or RAD51C (n = 1, 995) mutations, also displayed an increased contribution from CS-3." (PMID 31092228, 2019). "In cancer cells, mutated RAD51C recruits non-homologous end joining (NHEJ) proteins, which correlates to higher genomic instability due to error-prone repair." (PMID 31192117, 2019). "Because RAD51 and RAD51C are highly expressed in some cancer cell types, we hypothesized additional HR factors may also be upregulated in cancer cells and could represent valuable tools for transcriptionally targeting." (PMID 29549248, 2018). "Since Rad51C showed significant upregulation in cancer cells we proceeded to test whether Rad51C promoter is also hyperactive in cancer cells." (PMID 24742710, 2014). "In contrast, Rad51C promoter activity is on average over 225-fold stronger (with the maximum difference of 3,060-fold) in cancer cells than that in normal cells, which may lead to much higher tumor specificity." (PMID 24742710, 2014). "We found that expression of Rad51C was significantly elevated in the group of cancer cells." (PMID 24742710, 2014). "We found that Rad51C is significantly overexpressed in cancer cells." (PMID 24742710, 2014). "We have shown that Rad51C transcript and protein levels are elevated in cancer cells." (PMID 24742710, 2014). "Importantly, the size of Rad51C promoter required for differential expression in cancer and normal cells is only ~2 kb, which is within the range insert size that can be accommodated by most of viral vectors." (PMID 24742710, 2014). "Interestingly, the 2064 bp long Rad51C promoter fragment was approximately 300-fold higher in cancer cells than in normal cells." (PMID 24742710, 2014). "The analysis showed that Rad51C protein levels are up-regulated in cancer cells." (PMID 24742710, 2014). "Thus, in these patients with clear familial history of cancer, the evaluation of mutations in other genes, like PALB2, CHEK2 and RAD51C, should also be considered." (PMID 22655046, 2012). "Despite its importance in cancer development and therapy response, RAD51C functional studies have proven difficult due to its low cellular abundance, protein instability, embryonic lethality when deleted in mice, and essentiality in primary and most cancer cells." (PMID 37488098, 2023). "We therefore asked whether this phenomenon extended beyond FA and tested if somatic polygenic RAD51C + BRCA2 mutations in tumors of cancer patients without FA could similarly show functional synergism." (PMID 36906610, 2023). "Previous reports indicate that the cancer-specific promoters of RAD51 and RAD51C, two critical HR factors, hold great potential for cancer diagnosis and treatment, but whether the two promoters are suitable for transcriptionally targeting every type of tumor has not been analyzed." (PMID 29549248, 2018). "We further extended this framework to five additional cancer-related genes (VHL, ATM, BRCA1, RAD51C, and BAP1), establishing a generalizable framework for gene-specific VEP with potential applications in precision medicine." (PMID 41955512, 2026). "RAD51C promoter methylation was widespread across multiple cancer types, but HRD features were only observed for cases which contained high-level tumour methylation and LOH of RAD51C." (PMID 39055334, 2024). "A recent study used HRD-associated genomic patterns to provide evidence of HRD in 30 different cancer types, noting the presence of BRCA1 and RAD51C methylation." (PMID 39055334, 2024).
cancer (continued). "In conclusion, this pan-cancer study broadens our understanding of BRCA1 and RAD51C methylation and identifies important avenues for further exploration, especially due to significant therapeutic implications." (PMID 39055334, 2024). "We have found that the most altered cancer-related genes include NBN, RAD51C, BRIP1 (mostly with amplification events), and CDH1 (usually with losses or deep deletions)." (PMID 37239898, 2023). "The most altered cancer-related genes include NBN, RAD51C, BRIP1 (mostly with amplification events), and CDH1 (usually with losses or deep deletions)." (PMID 37239898, 2023). "Thus, single-allele deletions of RAD51 and RAD51C appear to be haplo-insufficient in limiting APOBEC-induced mutation, which further supports a model in which HR factors are used to bypass APOBEC-induced abasic sites to reduce APOBEC-signature mutations in multiple human cancer types." (PMID 37532520, 2023). "This chromosomal region contains several genes connected to cancers including EME1, BRCA1, ERBB2, NF1, RAD51C, BRIP1, BIRC5 and PPM1D." (PMID 34885154, 2021). "In this analysis, we evaluated the clinical presentation of over 3000 women with PVs in BRIP1, RAD51C, or RAD51D identified by a multigene hereditary cancer panel." (PMID 33926482, 2021). "Our results suggest that the RAD51C and RAD51D genes should be included in gene panel testing for TOC and BC to guide cancer surveillance and prevention." (PMID 32107557, 2020). "LOH of BRCA1/2, RAD51C or PALB2 was also found as a monoallelic event, mainly in ovarian (47%) and breast (49%) cancer patients." (PMID 33149131, 2020). "The pathogenic variant population frequencies used in the segregation analysis model were estimated to be 0.00022 for RAD51C and 0.00026 for RAD51D based on 42 325 cancer-free individuals from the UK Biobank exome sequencing data." (PMID 32107557, 2020). "The five classical RAD51 paralogs [RAD51B, RAD51C, RAD51D, XRCC2 and XRCC3] are important components of the homologous recombination pathway that preserves genomic integrity and protects against cancer." (PMID 31584931, 2019). "We found that XRCC2 expression is upregulated in nearly all types of cancers, to a degree comparable to RAD51 while much higher than RAD51C." (PMID 29549248, 2018). "One such strategy is to target tumors with cancer-specific, hyperactive promoters of HR genes including RAD51 and RAD51C." (PMID 29549248, 2018). "Amplifications of 8 FA genes are identified across 22 carcinomas; 2 of the carcinomas contain amplification in two FA genes (FANCG with FANCI and BRIP1 with RAD51C)." (PMID 26438152, 2015). "Here we have shown that Rad51C promoter is highly active in cancer cells and the pRad51C-DTA construct can target cancer cells with high selectivity." (PMID 24742710, 2014). "Therefore, this study aims to describe the age of onset and clinicopathological characteristics of BC and OC patients with a PALB2, RAD51C, or RAD51D GPV and compare these characteristics to national cancer registry data." (PMID 40428378, 2025). "Whilst the previously observed association between RAD51C methylation and HRD was validated for OV and TNBC, it was absent in other cancer types." (PMID 39055334, 2024). "Exploration of RAD51C methylation in the context of LOH and treatment-exposure would aid further characterisation with regard to its gene silencing effects, impact on HRD phenotype and therapeutic relevance across cancer types." (PMID 39055334, 2024).
cancer (continued). "Our results demonstrate that similar to the previously reported RAD51 and RAD51C promoters, pXRCC2-DTA may also serve as a valuable tool for cancer therapy." (PMID 29549248, 2018). "We found a frameshift mutation in RAD51C and deleterious mutations, one splicing and one frameshift, in two FANC members not previously associated with cancer risk, FANCD2 and FANCI, respectively." (PMID 29659569, 2018). "We found monoallelic functionally deleterious mutations in three genes of the FA family, namely RAD51C (FANCO), FANCD2 and FANCI genes, the latter two not previously associated with cancer risk." (PMID 29659569, 2018). "Similar to RAD51 and RAD51C, the XRCC2 promoter is hyperactivated in the group of cancer cells." (PMID 29549248, 2018). "This somehow indicates, that RAD51C is a susceptibility gene for HBOC and OC, but not for BrC and other cancers." (PMID 25343521, 2014). "Hence, cancer cells with heterozygous RAD51C promoter methylation likely retain HRR function, without the acquisition of the HRD phenotype." (PMID 39055334, 2024). "In other non-CIMP-driven cancer types, including other subtypes of BC, it is not clear whether the observed tumour BRCA1 or RAD51C methylation arose from constitutional methylation or from an early cancer-acquired event." (PMID 39055334, 2024). "Loss of the integral HR pathway components in cancers with non-BRCA HR defects due to germline or somatic mutations in PALB2, RAD51B, RAD51C, or RAD51D, or their inactivation through promoter methylation, might be the cause of olaparib susceptibility." (PMID 35741017, 2022). "The mutagenic processes result from loss of integral HR pathway components; therefore, cancers with non-BRCA HR defects, such as germline or somatic mutations in PALB2, RAD51B, RAD51C, or RAD51D, or their inactivation through promoter methylation, would also receive a positive treatment prediction." (PMID 31727117, 2019). "While most heterozygous carriers do not appear to have significantly increased cancer risks, susceptibility to cancer, including CRC, is well established for carriers of heterozygous pathogenic variants in FANCS/BRCA1, FANCD1/BRCA2, FANCN/PALB2, FANCJ/BRIP1, and FANCO/RAD51C." (PMID 41155398, 2025). "In addition to cancer-type-specific thresholds that reduce the number of unexplained cases, we demonstrated the importance of including the promoter methylation status of BRCA1 and RAD51C in order to evaluate the fraction of HRD cases that are explained by known causes." (PMID 35783256, 2022). "For comparison, no BRIP1, 2 RAD51C, and 2 RAD51D large mutations per ~ 11,000 subjects are reported in the gnomAD database, and 2 BRIP1, 5 RAD51C, and 3 RAD51D large mutations per ~ 10,000 cancer-free women older than age 70 are documented in the FLOSSIES database." (PMID 32359370, 2020). "Therefore, an RAD51C and RAD51D analysis should be implemented into the comprehensive multi-gene testing for high-risk OC patients, including early-onset OC patients without a family cancer history." (PMID 26057125, 2015). "Since HRD scarring was an infrequent event for RAD51C methylation beyond OV and TNBC, meRAD51C is unlikely to be relevant for most cancer types as a PARPi single-agent treatment biomarker." (PMID 39055334, 2024). "The other patient, who had a germline PV/LPV in RAD51C (detected also in the tumor) and in the ATM gene (not detected in tumor), had no family history of cancer." (PMID 35326583, 2022). "However, DNA fibre analysis showed, unlike effects observed in HR-deficient OVCAR8 RAD51C KO cells, forks stalled by hydroxyurea (HU) were not degraded in WEHICS62 cells, indicating fork protection, a mechanism associated with PARPi-resistance in BRCA1-deficient cancer cells." (PMID 32457376, 2020).
tumor (114 papers, 2014 to 2026). "The six BC tumours linked to RAD51C deleterious variants predominantly exhibited TNBC or HER2-negative immunohistochemistry profiles, and all were diagnosed in under-40 years old." (PMID 40282418, 2025). "BRCA1 and RAD51C promoter methylation also causes HRD but often incompatible with BRCA mutations in tumor tissue." (PMID 39334297, 2024). "Associations between HRD status and tumor subtype, age at diagnosis, and gene-specific loss of heterozygosity in RAD51C/D were investigated using logistic regression or the t test." (PMID 38648056, 2024). "This variant was inherited from the patient’s father but his family history was unsuspicious for other RAD51C-associated tumours." (PMID 37507557, 2023). "While xenograft take rates are lower for cells with A126T compared to G264S mutations, both mutant cells showed significantly decreased tumor volumes compared to cells containing wild-type RAD51C." (PMID 37488098, 2023). "Another tumor that was GI-positive with Myriad MyChoice had both a splice-disrupting variant in RAD51C and a pathogenic BRCA1 variant." (PMID 38067228, 2023). "Given its integral role in HRR, studies suggest that RAD51C shares many tumor characteristics associated with BRCA germline variants." (PMID 35626165, 2022). "This amplification is associated with overexpression of RAD51C and several other genes in a significant proportion of the primary tumours." (PMID 36293346, 2022). "The sensitivity of tumors with HRR mutations (HRRm), including BRCA1, BRCA2, PALB2, and RAD51C, to PARPi has been reported in preclinical research, as well as clinically, across tumor types." (PMID 36970052, 2022). "In this study, case–control analysis data were combined with tumour sequencing, in silico prediction tools, and pedigree segregation to assess the pathogenicity of RAD51C MS variants." (PMID 35039523, 2022). "While further studies are required for rare variants, integration of case–control data with tumour sequencing provides a powerful strategy to clarify the role of RAD51C MS variants in BC predisposition." (PMID 35039523, 2022). "Of these, 11 (19%) patients had BRCA1/2-mutated tumors (7 BRCA1 and 4 BRCA2), 2 (4%) patients had tumors with BRIP1 mutations, and 1 (2%) patient had a tumor with a two-copy deletion of RAD51C." (PMID 34552099, 2021). "One tumour showed an alteration in FANCA, one tumour showed an alteration in FANCM (with a concomitant BRCA1 P/LP variant), and one tumour showed an alteration in RAD51C." (PMID 34680387, 2021). "A total of 10 patients with a familiar predisposition for EOC and a known mutation in BRCA1, BRCA2 or RAD51C and available tumor tissue were included in the cohort." (PMID 33482905, 2021). "Hypermutated tumors were generally CSig3(–), with the single CSig3(+) tumor also notable for biallelic RAD51C loss." (PMID 34877933, 2021). "Similar to BRCA1/2, in cases where pathogenic mutations in RAD51C sensitize tumours to PARP inhibition, resistance mechanisms via the acquisition of secondary mutations have been reported." (PMID 36046263, 2020). "In previous studies we have also demonstrated complete or partial loss of wild-type alleles in tumour DNA from FC carriers of RAD51C c.705G>T; p.Lys235Asn, RAD51D c.620C>T; p.Ser207Leu and FANCI c.1813C>T; p.Leu605Phe also from the analyses of RRCancer biobank materials." (PMID 36969007, 2023). "Similarly, the proportion of variants that were present on tumor testing only varied widely by gene, with the highest proportion found in RAD51C (100%, N = 2) and CDH1 (90%, N = 9) and the lowest proportion found in CHEK2 (0%, N = 0)." (PMID 35962742, 2023).